LEP (leptin)
Diseases named in the same sentence as LEP in open-access papers (continued):
Sharing a sentence is not in itself a finding about the gene and the disease.
Hyperglycemia (continued). "Preclinical data suggest that statins may alter adipokine profiles—reducing leptin levels and increasing appetite—potentially contributing to weight gain and hyperglycemia (the so-called “gluttony statins” phenomenon)”." (PMID 40785972, 2025). "In 2011, we and others made an unexpected discovery: In rodent models of uncontrolled type 1 diabetes (T1D), the most severe manifestations of insulin deficiency — hyperglycemia and diabetic ketoacidosis (DKA) — can be fully reversed by infusing the adipocyte hormone leptin directly into the brain." (PMID 40759579, 2025). "This shows that glycemia affects serum leptin levels and that hyperglycemia lowers leptin levels." (PMID 38707092, 2024). "Additionally, the occurrence of hyperglycemia, elevated the levels of insulin and leptin also contribute to the induction of oxidative stress." (PMID 38603728, 2024). "This clinical finding was supported by our preclinical study, in which daily treatment with ACEI or ARB, but not CaB, prevented the development of DPN without affecting the hyperglycemia in leptin-deficient ob/ob mice, a T2DM model." (PMID 38200077, 2024). "Furthermore, smoking induced hyperglycemia and significant reductions in serum insulin and leptin levels." (PMID 37189762, 2023). "In addition, leptin resistance in obese patients leads to excessive energy intake and affects the secretion of insulin, thus forming a microenvironment of hyperglycemia at the maternal–fetal interface." (PMID 36615730, 2022). "This preadipocyte proliferation and adipose tissue regeneration is not reversed by blocking the hyperglycemia associated with the lipodystrophy either by administration of an SGLT2 inhibitor (this study) or administration of leptin." (PMID 35964946, 2022). "Previous studies have shown a relationship between leptin and glucose regulation in fishes; where treatment with exogenous leptin induces hyperglycemia in goldfish, (C. auratus,), rainbow trout (O. mykiss,), and tilapia (Oreochromis mossambicus,; Oreochromis niloticus,)." (PMID 35454105, 2022). "By contrast, B6-ob/ob mice, which carry a leptin mutation on the B6 background, do not develop hyperglycemia under +CH conditions due to induction of β-cell proliferation." (PMID 35328627, 2022). "However, hyperglycaemia was observed in subjects with homozygous dominant, ‘AA’ of leptin gene (p=0.0173)." (PMID 36128550, 2022). "In NK and NK-T cells, leptin secretion was also evaluated in response to hyperglycemia." (PMID 34360753, 2021). "After establishing stable T1D hyperglycemia, we delivered NachBac or control vectors bilaterally to the Arc of these mice, and at the same time implanted osmotic minipumps (2-week duration) for i.c.v. infusion of leptin or saline." (PMID 33976218, 2021). "Thus, leptin very efficiently ameliorated hyperglycemia in this new model of type 1 diabetes, probably through lowered hepatic glucose production resulting from lowered glucagon levels." (PMID 31743040, 2020). "Hyperglycemia triggers intracellular pathways, which promote tumor progression, such as increased leptin levels and pro-cell survival AKT/mTOR, enhancement of WNT/βcatenin signaling, induction of epithelial mesenchymal transition and upregulation of inflammatory cytokine levels in circulation." (PMID 33212778, 2020). "Taken together, these observations concerning UCP1 amounts and activity are therefore contrary to any hypothesis regarding a role for leptin-induced UCP1-mediated glucose combustion in BAT or brite/beige fat in the leptin-induced amelioration of hyperglycemia." (PMID 31743040, 2020). "Intriguingly, chronic i.c.v. leptin injection did not reverse hyperglycemia in insulin-deficient RIP-CreΔLEPR mice, suggesting that LEPRs in RIP-Cre25Mgn neurons play a critical role in glucose-lowering effects of leptin in an insulin-independent manner." (PMID 33071988, 2020). "After the development of hyperglycemia, a 3-wk period of treatment with leptin was initiated." (PMID 31743040, 2020).
Hyperglycemia (continued). "Our data suggest that glucagon signaling does not drive hyperglycemia in insulin-deficient mice lacking LEPRs in RIP-Cre25Mgn administered i.c.v. leptin." (PMID 33071988, 2020). "Although there was no noticeable difference in appetite of mice during weekly post-implantation monitoring, changes in leptin could be a result of the dramatic lowering of hyperglycemia." (PMID 32152396, 2020). "Leptin fully normalized hyperglycemia in standard chow-fed streptozotocin-treated diabetic mice." (PMID 31743040, 2020). "Consistent with a previous study, leptin levels in the pre-treatment diabetic patients with hyperglycemic crises were significantly lower than those in the control group; leptin levels increased significantly after hyperglycemia treatment." (PMID 30774721, 2019). "Importantly, stimulation of leptin synthesis is produced by hyperglycaemia, and potentially by meal-to-meal postprandial glycaemic spikes." (PMID 30241328, 2018). "Chronic hyperglycemia and leptin resistance, by promoting the generation of systemic proinflammatory cytokines and shortage of NO, probably exert an array of direct and indirect influences on the renal vascular bed, involving both myogenic and tubule-glomerular feedback responses." (PMID 29707583, 2018). "Loss of insulin-mediated intra-islet suppression of glucagon production may be a contributor to hyperglycemia in Akita mice, and leptin treatment appears beneficial in such a circumstance." (PMID 28702245, 2016). "However, chronic hyperglycaemia, in addition to fluctuations in glucose level and hyperinsulinaemia (particularly in fasting conditions), leptin resistance, and inflammation exacerbate ROS formation and maintain OS." (PMID 26918024, 2016). "Here, elevated melanocortin transcription in the hypothalamus of PLB4 mice may be a downstream effect of persistently increased circulating levels of leptin and systemic hyperglycaemia." (PMID 27138913, 2016). "Moreover, supplementation of this element markedly ameliorated the hyperglycemia of diabetic mice together with an increase in leptin production, and it appears that zinc is a mediator of leptin production." (PMID 24748223, 2014). "It has also been proposed that leptin resistance in β-cells could be involved in the abnormal response of these cells to sustained hyperglycemia." (PMID 23936486, 2013). "Finally, hyperglycemia also enhanced endogenous expression of leptin protein in all three cell lines." (PMID 24260287, 2013). "In relation to metabolic and hormonal parameters, although insulin, HOMA index, and leptin were similar between groups, the hypercaloric diet induced hyperglycemia (CD: 90.8 ± 1.4 vs. HD: 97.6 ± 2.4, p = 0.03) and impaired glycemic tolerance (CD: 27198 ± 451 vs. HD: 31867 ± 1463, p = 0.01)." (PMID 23587409, 2013). "Finally, the maturity-onset nature of hyperglycemia coupled with the less extreme plasma concentrations of insulin and leptin makes the polygenic models much more reflective of the most common forms of human T2D." (PMID 23671854, 2013). "Indeed, recent studies revealed that leptin has the effect to normalize hyperglycemia and hyperinsulinemia and to increase insulin sensitivity." (PMID 23579596, 2013). "Glucose-mediated enhancement of leptin signaling in breast tissue and other tissues throughout the body represents at least one mechanism by which hyperglycemia may result in worse cancer promotion and progression." (PMID 24260287, 2013). "Diet induced hyperglycemia while insulin and leptin levels remained unchanged." (PMID 23587409, 2013). "What could hence be hypothesized is a type of leptin resistance in the case of neonates of diabetic mothers as a result of persistent hyperglycemia and hyperinsulinemia, just as insulin resistance is a progenitor of diabetic pathology." (PMID 23227034, 2012).
Hyperglycemia (continued). "Also, they exhibited type 2 diabetic characteristics such as hyperglycemia, hyperleptinemia, and hyperinsulinemia compared with m/m mice, and Kangen-karyu administration significantly reduced serum glucose and leptin concentrations at a dose of 200 mg/kg." (PMID 22969821, 2012). "It is noteworthy that the Nidd1/of is quite a contrast to the Nidd2/of in that it did not contribute to any further hyperglycemia in the condition of leptin signaling deficiency." (PMID 23304119, 2012). "Furthermore, hepatocyte-selective genetic knockout of CB1R in mice led to reduced steatosis, hyperglycemia and insulin and leptin resistance on high-fat diet in the context of similar adiposity when compared to wild type mice on high-fat diet." (PMID 22870290, 2012). "Leptin resistance affects glucose homeostasis and contributes directly to hyperglycaemia." (PMID 22166251, 2011). "Indeed, oral leptin enhanced fructose-induced mild hyperglycaemia and the size of this effect is dependent on the amount of fructose absorbed." (PMID 19956534, 2009). "Indeed, when the same dose of leptin (3 ng/g) was combined with low amount of fructose (1 g/kg), an increase in fructose-induced hyperglycaemia was also observed but, at levels significantly lower than those levels seen with 2 g/kg fructose (data not shown)." (PMID 19956534, 2009). "Adipocytokines may also exert a metabolic role in postprandial hyperglycemia and therefore, systemic leptin was investigated in several studies." (PMID 17311679, 2007). "Postprandial hyperglycemia is associated with lower circulating leptin whereas resistin and adiponectin are not altered in slim, insulin-sensitive probands." (PMID 17311679, 2007). "Moreover, visceral fat accumulation may further disturb glucose homeostasis through abnormal secretion of metabolic regulators like retinol-binding protein-1 and leptin, exacerbating hyperglycemia-induced retinal damage." (PMID 40667435, 2025). "Additionally, CKD is associated with reduced insulin secretion and sensitivity, elevated adipokine levels such as leptin, and other CKD-related issues such as hyperparathyroidism and an inflammatory state, which contribute to an increased risk of hyperglycemia." (PMID 39439522, 2024). "In contrast to POMC neurons, deleting of Lepr in AgRP neurons produces hyperphagia and hyperglycemia, resulting in massive weight gain that reaches about 80% of the weight observed in db/db mice, suggesting AgRP neurons play important roles in mediating leptin’s effects on energy balance." (PMID 38027481, 2023). "In addition, leptin may also have insulin-independent effects to reverse hyperglycemia and ketoacidosis in poorly controlled T1DM animal models." (PMID 36674935, 2023). "Importantly, leptin administration via subcutaneous infusion pumps prevented the development of hyperglycemia in Aα4KO mice, indicating that leptin is able to prevent the metabolic abnormality associated with lipodystrophy, similar to other lipodystrophy mouse models." (PMID 36241662, 2022). "Additionally, factors such as hyperglycemia and hyperinsulinemia also facilitate leptin secretion." (PMID 34108008, 2021). "However, other GABAergic neuronal groups likely contribute to glucose-lowering effects as well, because intracerebroventricular (i.c.v.)leptin injection still can lower hyperglycemia in insulin-deficient mice lacking LEPRs in AgRP neurons." (PMID 33071988, 2020). "Leptin administration into the brain combined with acipimox, which lowers blood lipids by suppressing triglyceride lipase activity, can restore normal glycemia in insulin-deficient RIP-CreΔLEPR mice, suggesting that excess circulating lipids are a driving-force of hyperglycemia in these mice." (PMID 33071988, 2020).
Hyperglycemia (continued). "In fact, intrauterine exposure to hyperglycemia determines an impairment in placental cholesterol uptake and alters placental methylation of leptin and adiponectin, hormones that regulate energy balance and insulin sensitivity, leading to the development of both leptin and insulin resistance." (PMID 31572434, 2019). "However, two days after leptin delivery was halted hyperglycemia reappeared." (PMID 31391467, 2019). "However in women with COPD-BS were observed higher levels of insulin and leptin, which seems not be enough to diminish hyperinsulinemia and hyperglycemia, which the high risk of develop T2DM and other pathogenic effects is maintained." (PMID 30514305, 2018). "Furthermore, both cord-blood insulin as well as leptin > 90th percentile showed strong positive associations with maternal 3rd trimester hyperglycemia, but neither with pregravid BMI nor excessive GWG." (PMID 29925339, 2018). "In addition, loss of GluN2B in AgRP neurons of the morbidly obese and severely diabetic leptin-deficient Lepob/ob mice does not affect body weight and food intake but, remarkably, leads to full correction of hyperglycemia." (PMID 26500840, 2015). "In fact, systemic leptin administration at a dose that does not affect body weight and food intake was shown to ameliorate hyperglycemia in ob/ob mice [these mice are characterized by a mutation in the gene encoding for leptin (ob gene) and are leptin deficient]." (PMID 24589844, 2014). "Central leptin insufficiency due to dietary and lifestyle changes for extended periods of time has been shown to result in increased fat accrual, decreased energy expenditure, hyperinsulinemia, hyperglycemia, neuroendocrine disorders, osteoporosis, and impaired memory." (PMID 22518191, 2012). "The use of ob/ob animals has shown the involvement of catecholamines and serotonin (5-HT) in the leptin-deficient syndrome: in mutant animals, dopaminergic agonists reduce food intake and restrain metabolic dysfunctions, while SSRI antidepressant treatment decreases hyperphagia and hyperglycemia." (PMID 21299850, 2011). "A 10-week continuous HFD feeding produced robust weight gain, hyperglycemia, and elevated levels of total cholesterol (TCHO), triglycerides (TG), HDL-C, and leptin." (PMID 41244820, 2025). "In the present research, HSHF not only induced the formation of hyperglycemia but also increased the levels of serums TC, TG, LDL-C, resistin, and LEP, and decreased the level of ADPN." (PMID 37569125, 2023). "Hyperglycemia, hyperinsulinemia, HOMA-IR, and insulin tolerance were normalized after leptin treatment." (PMID 36046814, 2022). "Moreover, leptin administration has achieved promising results in insulin-deficient rodent models, which indicated leptin could reverse hyperglycemia independent of insulin." (PMID 34996484, 2022). "To examine the role of AMPK activation in T1D hyperglycemia, we treated STZ-induced T1D mice, in which glucose levels were normalized by i.c.v. leptin infusion, with saline or AICAR, a specific agonist of AMPK." (PMID 33976218, 2021). "Finally, hyperglycemia or hyperinsulinemia might stimulate leptin secretion from PBMCs." (PMID 34360753, 2021). "While all mice had similar hyperglycemia following STZ injections, leptin therapy induced more rapid normalization in blood glucose levels in the knockdown mice." (PMID 30824713, 2019). "Genetic modifications (e.g., eNOS-/-, leptin resistant db/db) and STZ treatment accelerate the renal injury by contributing to hyperglycemia and glomerular hyperfiltration." (PMID 30405076, 2018). "Moreover, their preclinical study shows that continuous systemic leptin administration ameliorates hyperglycemia and that it can reduce dosage of insulin for anti-diabetic treatment, suggesting that leptin may be applicable in the clinical setting as an adjuvant to insulin therapy." (PMID 25870537, 2015).
Hyperglycemia (continued). "Tofogliflozin prevented fat accumulation and reduced plasma leptin level in DIO rats, and improved hyperglycemia and hyperinsulinemia in KKAy mice." (PMID 25000147, 2014). "Akt2 knockout mice exhibited a diabetic phenotype accompanied by hyperglycemia, impaired INS action, reduced circulating leptin, and mild growth retardation, whereas Akt2 and Akt3 double knockout mice exhibited hyperinsulinemia, hyperglycemia, and reduced brain volume." (PMID 39984861, 2025). "According to a previous report, ob/ob mice exhibit basal hyperglycemia due to a lack of the leptin gene." (PMID 40141314, 2025). "In this model, severe hyperglycemia did not modify the secretion of the main inflammatory (chemerin and leptin) and anti-inflammatory (adiponectin) placental adipokines." (PMID 36982317, 2023). "When leptin administration was stopped, hyperglycemia was quickly reestablished in the absence of changes in insulin, indicating the central effect of leptin on the modulation of glucose metabolism." (PMID 35052794, 2022). "In addition to wasting syndrome, ob/ob mice exhibit a phenotype of hyperglycemia, similar to human T2DM patients, indicating that leptin plays an important role in regulating glucose metabolism." (PMID 35933481, 2022). "Strikingly, i.c.v. leptin infusion failed to reduce T1D hyperglycemia in NachBac-injected Vgat-Cre mice, while it maintained its normal effects in reducing glucose in GFP-injected Vgat-Cre mice." (PMID 33976218, 2021). "Although leptin administration decreased hyperglycemia and partially preserved muscle mass, ob/ob mice do not dramatically improve muscle mass." (PMID 34064680, 2021). "The presence of AgRP neurons is not required for T1D hyperglycemia or for the observed leptin action." (PMID 33976218, 2021). "Consistently, leptin infusion failed to reduce blood cort levels in the groups with failed reduction of T1D hyperglycemia." (PMID 33976218, 2021). "This includes blood glucose from hypoglycemia to hyperglycemia, osmolality, natremia, lipids, proteins, amino acids, and the hormones glucagon, GLP-1, leptin, and CCK." (PMID 33495245, 2021). "According to glucose metabolism, leptin has been long related to glucose homeostasis improving insulin sensitivity, since intra-VMH injection of leptin increases glucose uptake in peripheral tissues and normalizes hyperglycemia." (PMID 34201257, 2021). "Cowley's group observed, in a recent study of DIO mice, that leptin signaling in ARC neurons (most likely AgRP neurons) blocked the suppressing effect of insulin on hepatic glucose production through upregulation of PTP1B, leading to hyperglycemia." (PMID 32731387, 2020). "The high-fat diet alone only tended to increase leptin and insulin levels while it did induce hyperglycemia, but no significant increase of HOMA-IR." (PMID 31332243, 2019). "Our results in adult ZDF rats indicate that reduced leptin sensitivity is not sufficient to prevent hyperinsulinemia- and hyperglycemia-induced pulmonary vascular dysfunction." (PMID 30689673, 2019). "Therefore, insulin and leptin resistance of HFD AD mice lead to hyperleptinemia, hyperglycemia, and hyperphagia in a vicious cycle and ultimately the worsened metabolic stresses." (PMID 30096853, 2018). "The lack of appetite control in the leptin-deficient BTBR ob−/ob− mice led to an increase in both body weight and degree of hyperglycaemia over time." (PMID 30094465, 2018). "After an overnight fast, CRF-OE mice have hyperglycemia, maintain elevated leptin plasma levels, show no rise in acyl ghrelin, and inhibit refeeding response compared to WT mice." (PMID 28101317, 2017). "In Akita mice, whereas a brief treatment with exendin-4 resulted in no apparent improvement in hyperglycemia, leptin treatment resulted in restoration of normoglycemia." (PMID 28702245, 2016). "Mice lacking leptin suffer from enormous weight gain, hyperglycaemia, hyperinsulinemia and glucose intolerance." (PMID 25144618, 2014).